MIR5683 (microRNA 5683)
Synonyms: hsa-mir-5683
Gene: MicroRNA gene on chromosome 6 (6,169,334 to 6,169,409, forward strand). Ensembl gene ENSG00000283616.
Diseases named in the same sentence as MIR5683 in open-access papers:
MIR5683 is named in the same sentence as 1 disease in open-access papers, as found by Europe PMC text mining. Sharing a sentence is not in itself a finding about the gene and the disease.
MIR5683 shares sentences with these, for which no sentence is quoted: thrombosis (1 paper).